MIR4432 (microRNA 4432)
Synonyms: hsa-mir-4432
Gene: MicroRNA gene on chromosome 2 (60,387,362 to 60,387,445, reverse strand). Ensembl gene ENSG00000266078.
Homologues: Orthologues: chimpanzee MIR4432 (100% identical).